L1CAM (L1 cell adhesion molecule)
Diseases named in the same sentence as L1CAM in open-access papers (continued):
Sharing a sentence is not in itself a finding about the gene and the disease.
prostate carcinoma (8 papers, 2014 to 2025). A carcinoma that arises from epithelial cells of the prostate gland. "L1CAM expression has been rarely analyzed in prostate cancer, where it has been associated with androgen-insensitive prostate cancer and high metastatic potential." (PMID 33291528, 2020). "In vivo targeting of L1CAM expression using liposome-encapsulated L1CAM siRNAs effectively inhibited prostate cancer growth in mouse bone, which was associated with decreased L1CAM expression and cell proliferation by tumor cells." (PMID 25294816, 2014). "To understand the mechanisms underlying the antimetastatic action of L1CAM gene targeting of prostate cancer, we stably downregulated L1CAM expression in PC3 cells using lentiviral vector-delivered shRNA and examined the behavior of cells at different steps of the metastatic cascade in vitro." (PMID 25294816, 2014). "Considering that DU145 and PC3 cell lines are derived from prostate cancer metastases at distant sites and express the L1CAM, we next examined whether L1CAM expression was associated with the status of prostate cancer distant metastasis." (PMID 25294816, 2014). "To examine whether the L1CAM is associated with prostate cancer progression, we first analyzed L1CAM expression in normal and several available prostate cancer cell lines by Western blotting and a flow cytometric analysis." (PMID 25294816, 2014). "There is currently an open phase I clinical trial evaluating autologous lentivirally induced L1CAM T cells in prostate cancer." (PMID 41301074, 2025). "Similar results were obtained in DU145 prostate cancer cell line that normally express L1CAM, supporting the critical role of L1CAM in migratory and invasive property of prostate cancer." (PMID 25294816, 2014). "The correlation between L1CAM expression and prostate cancer metastasis was also validated in serum samples of prostate cancer patients." (PMID 25294816, 2014). "Knockdown of L1CAM expression in prostate cancer cells by RNA interference significantly decreased their aggressive behaviors, including colony formation, migration and invasion in vitro, and tumor formation in a metastatic murine model." (PMID 25294816, 2014). "Herein, we demonstrated that the L1CAM was expressed in androgen-insensitive and highly metastatic human prostate cancer cell lines." (PMID 25294816, 2014). "Interestingly, oxidative stress triggered in human prostate cancer PC3 cells by hydrogen peroxide at the concentration of 10 mM results in an increase in L1CAM levels." (PMID 40710351, 2025). "Since inactivating L1CAM in prostate cancer inhibits metastases, this strategy could be an additional potential targeted therapy to be applied in tumors with known aggressive potential." (PMID 33291528, 2020). "To determine whether the reduction of prostate cancer invasiveness by L1CAM shRNA is through a reversal of the EMT, we evaluated expressions of genes associated with EMT phenotypes at the protein level." (PMID 25294816, 2014). "Alternatively, we examined whether L1CAM expression was correlated with the cancer metastasis status using sera from normal populations and prostate cancer patients with localized tumors or bone metastases." (PMID 25294816, 2014). "To date, there is limited literature on the link between the L1CAM and prostate cancer." (PMID 25294816, 2014). "Levels of increased vimentin and decreased E-cadherin were correlated with the L1CAM knockdown effectiveness of shRNA, revealing an undescribed mechanism of the L1CAM on prostate cancer metastasis that contradicts its known function of promoting the EMT seen in other cancer types." (PMID 25294816, 2014). "In clinical specimens, mean serum L1CAM levels in bone-metastatic prostate cancer patients (45.0±27.2 ng/ml, n=19) were significantly higher than those in patients with prostate-confined tumors (28.4±22.2 ng/ml, n=30, p<0.05) and normal controls (12.1±8.6 ng/ml, n=10, p<0.001)." (PMID 25294816, 2014).
prostate carcinoma (continued). "This study has, for the first time, shown that patients who develop skeletal metastasis from prostate cancer tend to have the highest levels of the L1CAM, a finding potentially useful for clinical practice in the early diagnosis of prostate cancer bone metastasis." (PMID 25294816, 2014). "To assess whether L1CAM can be a novel RNAi target for prevention or treatment of disseminated prostate cancer, we knocked down L1CAM expression in highly metastatic PC3 cells using siRNA." (PMID 25294816, 2014). "We examined whether the abundant L1CAM overexpression influences the mobility of prostate cancer cells by transwell migration assay." (PMID 25294816, 2014). "We further examined whether siRNA-mediated inhibition of L1CAM expression represents a promising antigrowth and antimetastatic strategy for prostate cancer gene therapy, particularly for bone metastases." (PMID 25294816, 2014). "Besides, knockdown of L1CAM significantly decreased colony formation of prostate cancer cells." (PMID 34228897, 2022). "To test whether L1CAM shRNA-mediated inhibition of prostate cancer metastasis is a critical mediator of disseminating prostate cancer cells survival in circulation, we first compared the ability of PC3 cells with or without L1CAM shRNA expression to form cell aggregates in single-cell suspensions." (PMID 25294816, 2014). "Future studies of gene array patterns induced by the L1CAM and AKT/NF-κB should provide more information on understanding the molecular mechanism of prostate cancer bone metastasis." (PMID 25294816, 2014). "In human prostate cancer PC3 cells, L1CAM knock-down leads to a decrease in the expression of bcl-2 interacting protein 3 and different antioxidant enzymes that are important for ROS homeostasis including catalase, GPX1, GPX2, GPX4, GRP78, NOX5, SOD1, SOD2, and BIRC5." (PMID 40710351, 2025). "The L1 cell adhesion molecule (L1CAM) has been implicated in tumor progression of many types of cancers, but its role in prostate cancer and its application in targeted gene therapy have not been investigated." (PMID 25294816, 2014). "An ELISA analysis of L1CAM levels in conditioned media from PC3 and DU145 cells (296.1±0.67 and 29.0±1.34 ng/ml, respectively) confirmed that the ectodomain was shed by metastatic prostate cancer cells." (PMID 25294816, 2014). "However, the biological function of the L1CAM in human prostate cancer has not yet been determined and remains to be excluded." (PMID 25294816, 2014).
retinoblastoma (8 papers, 2013 to 2025). A malignant tumor that originates in the nuclear layer of the retina. "The study presented focuses on the role of the neuronal cell adhesion molecule L1 cell adhesion molecule (L1CAM) in retinoblastoma (RB), the most common malignant intraocular childhood tumor." (PMID 34228897, 2022). "Recently, L1CAM has been reported to be both sufficient and necessary for conferring chemoresistance to retinoblastoma, the most common intraocular cancer in children." (PMID 32429448, 2020). "Along this line, L1CAM depletion in retinoblastoma cells resulted in a marked increase of the pro-apoptotic proteins which cleaved caspase-3 and cytochrome C, whereas the anti-apoptotic proteins Bcl-2, Bcl-xL, and pro-caspase-3, were reduced." (PMID 32429448, 2020). "Immunofluorescence staining with SSEA-5 and L1CAM was carried out on tissue arrays of retinoblastoma, embryonic tumors, and adult tumors." (PMID 26317026, 2013). "Retinoblastoma displayed predominantly L1CAM staining, with some areas of SSEA-5 staining." (PMID 26317026, 2013). "We investigated the role of the neuronal L1 cell adhesion molecule (L1CAM) in retinoblastoma (RB), a malignant intraocular childhood tumor." (PMID 34228897, 2022).
ovarian tumor (7 papers, 2011 to 2021). "L1-CAM/CE7 expression was next evaluated on different histological subtypes of primary patient-derived ovarian tumor specimens by immunohistochemical staining of 40 cases of ovarian tumor tissue microarray." (PMID 26761817, 2016). "We have previously demonstrated that anti-L1CAM RIT using the mAb chCE7 is effective against small disseminated ovarian tumour nodules in a preclinical setting." (PMID 26116117, 2014). "The introduction of PTX in the therapy scheme of L1CAM-targeted 177Lu-DOTA-chCE7 RIT may provide a potential clinical setup against residual ovarian tumour nodules after first-line tumour resection." (PMID 26116117, 2014). "As a new CSC target, the combination of The L1 cell adhesion molecule (L1CAM) and CD133 defines a new cancer cell population of ovarian tumor‐initiating cells." (PMID 34766149, 2021). "Based on their high background staining in tumor-negative tissues and heterogenous expression patterns in primary ovarian tumors, EGFR, VEGF-A and L1CAM were excluded from further analyses." (PMID 32545676, 2020). "For ovarian tumors, there is little specific information that ascertains the involvement of MCAM, L1CAM (CD171), EpCAM, IgLON, and ALCAM/CD166 (Activated Leukocyte Cell Adhesion Molecule)." (PMID 26339605, 2015). "With respect to the primary ovarian tumors, EGFR, VEGF-A and L1CAM were heterogeneously expressed." (PMID 32545676, 2020).
Aqueductal stenosis (6 papers, 2019 to 2025). Stenosis of the cerebral aqueduct (also known as the mesencephalic duct, aqueductus mesencephali, or aqueduct of Sylvius), which connects the third cerebral ventricle in the diencephalon to the fourth ventricle, which is between the pons and cerebellum. "This included one case of suspected L1CAM mutation where the iuMR was able to demonstrate multiple findings (i.e. ventriculomegaly, dysmorphic cerebellum, kinked brainstem, aqueductal stenosis)." (PMID 31076826, 2019).
cholangiocarcinoma (6 papers, 2013 to 2020). A carcinoma that arises from the intrahepatic biliary tree (intrahepatic cholangiocarcinoma) or from the junction, or adjacent to the junction, of the right and left hepatic ducts (hilar cholangiocarcinoma). "Our study is the first to show an enhanced therapeutic effect of a therapeutic antibody targeting L1CAM in combination with chemotherapy in cholangiocarcinoma models." (PMID 28166242, 2017). "Our study is the first to show a therapeutic effect of anti-L1CAM mAb in combination with chemotherapy in cholangiocarcinoma model." (PMID 28166242, 2017).
metastatic disease (6 papers, 2020 to 2022). "In the present case series, L1CAM high expression was found in 62.30% of the cranial metastatic tumors from lung adenocarcinoma, with low expression in 37.70% of tumors." (PMID 35525225, 2022). "Among these patients, L1CAM had high expression found in 62.30% (n = 38) of the cranial metastatic tumors, and low expression in 37.70% (n = 23) tumors." (PMID 35525225, 2022). "Moreover, the identification of L1CAM as a marker of metastasis-initiating cells, not expressed in the normal colonic epithelium, may open new therapeutic avenues for lethal metastatic disease." (PMID 33673710, 2021).
schizophrenia (6 papers, 2018 to 2025). A major psychotic disorder characterized by abnormalities in the perception or expression of reality. "A Japanese study found that L1CAM gene mutation of some base pairs are positively correlated with male schizophrenia, but has nothing to do with female schizophrenia." (PMID 41573035, 2025). "For example, for the schizophrenia-specific signature, the enriched pathways included ‘L1 cell adhesion molecule interactions ’, ‘chaperone mediated autophagy ’ and other relevant processes." (PMID 36073911, 2022). "Of 1,183 genes that mapped to nominally significant DMPs, some were previously associated with BD or schizophrenia, including MLC1, ESR1, KCKN5, L1CAM, CPEB1 and GABBR2." (PMID 35922419, 2022). "Similarly, mutations in genes involved in synaptic targeting by ChCs onto the AISs of pyramidal neurons including L1CAM, ERBB4, and FGF13 have been implicated in epilepsy, schizophrenia or intellectual disability." (PMID 34630048, 2021).
brain tumor (5 papers, 2010 to 2024). "For example, short hairpin RNA targeting L1CAM, which has been found to impair axon outgrowth in normal neurons, can disrupt cell proliferation and neurosphere formation of brain tumor cells." (PMID 20840789, 2010). "As is the case for our in vitro motility results, it is tempting to hypothesize that the reduced invasion in vivo was due to the disruption of L1CAM function, which we previously have shown to be important for the invasion of T98G cells in our chick embryo brain tumor model." (PMID 39518060, 2024).
endometrioid carcinoma (5 papers, 2018 to 2025). "The authors found that endometrioid carcinomas with high-intermediate risk clinicopathological features behaved aggressively in the case of L1CAM positivity in more than 10% of tumor cells." (PMID 35892892, 2022). "Endometrioid adenocarcinoma specimens from 142 patients were tested for L1CAM and HER2 expression, revealing 27% and 12% positive cases, respectively." (PMID 40870967, 2025). "In conclusion, L1CAM is often expressed in MELF glands of endometrioid carcinoma, suggesting its involvement in the development of the MELF pattern." (PMID 35892892, 2022). "Clinicopathologic characteristics of 47 endometrioid carcinomas of endometrium according L1CAM expression." (PMID 30557309, 2018). "We evaluated L1CAM expression in 58 cases of uterine-confined, low-grade endometrioid carcinomas." (PMID 35892892, 2022). "In uterine-confined, low-grade endometrioid carcinomas, L1CAM overexpression in MELF glands may predict lymph node involvement." (PMID 35892892, 2022). "For instance, it has been shown that the Wnt/β-catenin pathway (which is often altered in low-grade endometrioid carcinomas) may regulate L1CAM expression." (PMID 35892892, 2022). "For instance, a L1CAM expression ≥10% in MELF glands might have a prognostic significance similar to LVSI; uterine-confined, low-grade endometrioid carcinoma with L1CAM positive glands might be included in the high-intermediate risk category according to the ESGO-ESTRO-ESP risk classifier." (PMID 35892892, 2022). "The authors found 10% L1CAM expression in stage I endometrioid adenocarcinomas, 18% in 160 advanced-stage endometrioid adenocarcinomas, and 75% expression in non-endometrioid carcinomas." (PMID 40870967, 2025). "Patients with L1CAM-positive endometrioid carcinomas showed shorter recurrence-free survival in the univariate analysis, and despite a multivariate analysis mentioned in the discussion, these data are not presented to further understand the independent or non-independent role of L1CAM expression." (PMID 40870967, 2025).
hepatocellular carcinoma (5 papers, 2012 to 2022). A malignant tumor that arises from hepatocytes. "However, no data of L1CAM are available for hepatocellular carcinoma (HCC)." (PMID 22888955, 2012).
Intellectual disability (5 papers, 2018 to 2023). "Females heterozygous for an L1CAM pathogenic variant may manifest minor features, such as adducted thumb and/or mild intellectual disability and, rarely, the complete MASA syndrome phenotype." (PMID 34206215, 2021).
rhabdomyosarcoma (5 papers, 2016 to 2025). A rare aggressive malignant mesenchymal neoplasm arising from skeletal muscle. "Interestingly, L1CAM has previously been identified as part of a high-risk gene signature in the pediatric cancer Rhabdomyosarcoma." (PMID 33196691, 2020). "L1CAM is also an adverse prognostic factor in Rhabdomyosarcoma, the most common pediatric soft tissue sarcoma." (PMID 33196691, 2020).
triple-negative breast carcinoma (5 papers, 2014 to 2025). An invasive breast carcinoma which is negative for expression of estrogen receptor (ER), progesterone receptor (PR), and human epidermal growth factor receptor 2 (HER2). "There are reports that inhibition of L1CAM reverses cisplatin resistance in triple-negative breast cancer cells." (PMID 36338974, 2022). "Expression of the L1 cell adhesion molecule (L1CAM, CD171) is associated with negative prognosis in triple-negative breast cancers." (PMID 41149583, 2025).
uterine cancer (5 papers, 2014 to 2023). Primary or metastatic malignant neoplasm involving the uterine corpus and/or the cervix. "Studies showed that the L1CAM could be used as a biomarker for ovarian and uterine carcinomas associated with poor clinical outcome." (PMID 32742486, 2020). "For instance, Mina Fogel and his workmate also revealed that the overexpression of L1CAM was associated with poor prognosis in ovarian and uterine carcinomas and could sever as a new factor for predicting patient survival and disease progresses." (PMID 32509846, 2020). "The ectodomain of the L1CAM can be shed and detected in serum samples of ovarian and uterine cancer patients." (PMID 25294816, 2014). "The process of L1CAM cleavage, mediated by proteases, mainly ADAM10, enhances the ovarian and uterine cancer cell migration on various extracellular matrix components through autocrine/paracrine binding to integrins." (PMID 27832351, 2017). "The disintegrin and metalloprotease (ADAM) family cleaves the transmembrane ectodomain of L1CAM extracellularly, releasing a soluble L1CAM ectodomain (L1CAM-ECD) of ~200 kDa from the cell surface, which has been detected in serum samples from patients with ovarian and uterine cancers." (PMID 37015905, 2023). "Although it is not surprising in the case of “type 2” uterine cancers, strikingly, despite potentially good prognosis, type 1 endometrioid cancers, positive for L1CAM, behave in the same manner as type 2 cancers with poor prognosis and short time to recurrence." (PMID 27832351, 2017).
cognitive deficit (4 papers, 2019 to 2025). "Of note, SVHRSP treatment also enhanced L1CAM expression, suggesting that SVHRSP may prevent synaptic loss, seizure development, and cognitive deficits by regulating the expression of the multifunctional L1CAM." (PMID 40723903, 2025). "To further investigate its effects on chronic epilepsy and the accompanying cognitive impairment, we studied the neuroprotective effects of SVHRSP in a kainic acid (KA)-induced chronic epilepsy model, with a particular focus on its potential association with L1CAM in the pathogenesis of epilepsy." (PMID 40723903, 2025). "For these reasons, in the current study, neuron-derived exosomes were extracted using the anti-CD171 (L1CAM) antibody from the serum samples of 15 mild and 18 moderate AD cases and 21 volunteers without any cognitive deficit." (PMID 36422510, 2022).
dementia (4 papers, 2014 to 2024). Loss of intellectual abilities interfering with an individual's social and occupational functions. "Because L1CAM is primarily expressed in neurons of both the central and peripheral nervous system, we cannot exclude the possibility that L1EVs are partly derived from postganglionic autonomic nerves that are pathologically affected early in PD and related dementia." (PMID 38048087, 2024). "Specifically, α-synuclein content in L1CAM-positive exosomes is similarly elevated (data shown as mean±SD) in RBD (26.69±12.82 pg/mL), motor PD (27.44±18.82 pg/mL) and PD with dementia (PDD 26.76±17.25 pg/mL) when compared with healthy subjects (HC, 12.71±5.93 pg/mL)." (PMID 32273329, 2020). "The levels of L1CAM and NCAM were found to be higher in the cerebrospinal fluid (CSF) of VaD, AD and MIX dementia patients compared to non-demented controls." (PMID 24448401, 2014).